CD4 (CD4 molecule)
Diseases named in the same sentence as CD4 in open-access papers (continued):
Sharing a sentence is not in itself a finding about the gene and the disease.
Cirrhosis (continued). "In conclusion, this study demonstrates that, in compensated and, to a lesser extent, decompensated cirrhosis, CD4+ and CD8+ T cells are skewed towards an activated and dysfunctional phenotype." (PMID 41028194, 2025). "With regard to CD4+ T cells, TNFα expression in decompensated cirrhosis patients was marginally elevated in comparison with compensated patients." (PMID 41028194, 2025). "This study revealed an upregulation of CD52 expression in peripheral blood pan CD4+ T cells in patients with acute decompensation of cirrhosis, correlating with disease severity and 90-day mortality." (PMID 39276679, 2024). "Of note, CD8+ T cells were enriched in the ascites of patients with decompensated cirrhosis, whereas CD4+ T cells were decreased." (PMID 38882602, 2024). "As circulating T cells have previously been shown to contribute to systemic inflammation and play a critical role in patients with cirrhosis, in this study, we examined the CD4+ as well as CD8+ T-cell compartment in detail, focusing on the peritoneal cavity." (PMID 38882602, 2024). "This study aimed to investigate the function of CD52 on CD4+ T cells on the blood of patients with acute decompensation of cirrhosis." (PMID 39276679, 2024). "CD52 expression was elevated in CD4+ T cells in acute decompensation of cirrhosis, and this elevation was correlated with increased disease severity and mortality." (PMID 39276679, 2024). "In line with recent research we report the median fraction of MAIT cells to be less than one percent of CD3+CD4- cells in patients with cirrhosis." (PMID 38691552, 2024). "Liver resident CD4+ T-cell subpopulations were contracted in cirrhosis, although they showed a pro-inflammatory Th17 profile." (PMID 39656486, 2024). "In healthy individuals, the median MAIT cell fraction was 6.1% out of CD3+CD4- cells compared to a median MAIT cell fraction of 0.8% (p<0.01) in all individuals with cirrhosis." (PMID 38691552, 2024). "The effect of different lesions on the effector phenotype of CD4+/CD8+ T cells was not completely consistent, Acute/AFL_HCC/Chronic/Cirrhosis/HBsAg_high/HCC/NAFL_HCC were seen to inhibit effector CD4+/CD8+ T cells, and NAFL inhibited effector CD8+ T cells." (PMID 38032223, 2024). "The ratio CD4+/CD8+ T cells in the liver of cirrhotic mice was significantly downregulated during cirrhosis." (PMID 39656486, 2024). "As in the liver, the ratio CD4+/CD8+ T cells in the brain of cirrhotic mice was significantly downregulated during cirrhosis." (PMID 39656486, 2024). "In more detail, in line with previous reports, we found that CD4+ as well as CD8+ T cells were decreased in the blood of patients with decompensated cirrhosis compared with healthy controls." (PMID 38882602, 2024). "It has been previously reported that the infiltration of CD4+ memory T cells contributed to immune microenvironment changes in cirrhosis." (PMID 37296834, 2023). "In conclusion, we proposed that the reduction in the CD8+ T cluster and NK cells, as well as the infiltration of CD4+ memory T cells, contributed to immune microenvironment changes in cirrhosis." (PMID 35903097, 2022). "In conclusion, we proposed that the reduction of the CD8+ T cell cluster and NK cells, as well as the infiltration of CD4+ memory T cells, contributed to immune microenvironment changes in cirrhosis." (PMID 35903097, 2022). "CD8+ T cells and NK cells were significantly decreased in patients with cirrhosis, while CD4+ T memory cells were increased." (PMID 35903097, 2022). "From cirrhosis to cancer, macrophages and naïve CD4 + T cells employ autocrine and paracrine mechanisms to communicate in the IL16 signaling pathway." (PMID 36221095, 2022). "On the one hand, this interaction became active in cirrhosis and cancer; on the other hand, the differentiation of Treg cells from naïve CD4 + T cell occurred first in cirrhosis and then became more obvious in cancer." (PMID 36221095, 2022).
Cirrhosis (continued). "Here, we establish the presence, regulation and mechanism of action of a suppressive CD4+ T cell subset expressing human leucocyte antigen G (HLA-G) in patients with acute decompensation of cirrhosis (AD)." (PMID 34344786, 2022). "The ligand-receptor pair of IL16 and CD4 is activated in the interaction of macrophages and naïve CD4 + T cells, and in conversion from cirrhosis to the cancer." (PMID 36221095, 2022). "The SVR rates were similar across subgroups defined by age, CD4 cell count, cirrhosis, HCV genotype and HIV transmission group." (PMID 36562643, 2022). "It has been found that the numbers of circulating CD4+T lymphocytes were significantly higher in HBV-associated HCC patients than that in chronic hepatitis B (CHB), HBV-related cirrhosis patients, and healthy individuals." (PMID 34566989, 2021). "In the present study, we showed that LSECs were versatile antigen-presenting cells able to differentiate a CD4+ Th17 adaptive response in the inflammatory context of CCl4-induced experimental cirrhosis." (PMID 32429209, 2020). "An interesting result of the present study was LSECs’ ability to differentiate CD4+ T cells towards pro-inflammatory pathways in CCl4-induced cirrhosis." (PMID 32429209, 2020). "The number and composition of CD4+ T cells was also affected in cirrhosis of various etiologies: lowered CD4+ T cells counts were associated with splenomegaly, thrombocytopenia and leukopenia." (PMID 33036244, 2020). "The decrease of CD4+ T cells in acutely decompensated cirrhosis/ACLF was based on reductions of naïve and effector CD4+ T cells, whereas central memory and effector memory CD4+ T cells were not reduced or even increased, respectively." (PMID 33574809, 2020). "Overall, the majority of patients were males, had cirrhosis, a relatively preserved immune status (CD4 >250 cells/mm3), were virologically suppressed (HIV-1 load <50 copies/mL), and had abnormal transaminase levels." (PMID 32121164, 2020). "There was a decrease in CD8+ T cells and a slight but significant increase in the CD4+ T-cell population in patients with cirrhosis." (PMID 29858567, 2018). "Coinfection with HIV and HBV is associated with a higher rate of HBV reactivation and an increased incidence of cirrhosis and death from cirrhosis in cases with low CD4 counts." (PMID 28836955, 2017). "In contrast, other studies have shown that coinfection was associated with higher risk of cirrhosis, HCC, liver decompensation and death, particularly in those with low CD4+ T cell counts." (PMID 28759595, 2017). "Based on these observations, we suggest that potent immunotherapy targeting Th17 cells and CD4+ CD25+ Foxp3+ Tregs and the inhibition of PGE2 secretion from HSC can slow the progress of LF and cirrhosis and other associated complications." (PMID 28399886, 2017). "Older age, male gender, male homosexuality, high CD4, undetectable HIV-RNA, CDC stage A-B, and severe fibrosis/cirrhosis were associated with a higher treatment initiation rate." (PMID 27450098, 2016). "Some also have a low CD4 due to a co-morbidity such as Hepatitis C and cirrhosis despite virologic suppression." (PMID 25369887, 2015). "Independent variables were age, sex, IL28B, −238 TNF-α and −592 IL-10 polymorphisms, HCV genotype, HCV-RNA levels, significant fibrosis or cirrhosis and CD4+ T cell count." (PMID 25013899, 2014). "CD4+IL-21+ T cell frequency in the CHB group was higher compared with the cirrhosis group and correlated with the peripheral blood lymphocyte counts." (PMID 24669269, 2014). "e) Patients were carefully evaluated for every one of the different known factors influencing the evolution to cirrhosis (age, sex, ethanol abuse, CD4+ T cell count at diagnosis and at inclusion, antirretroviral therapy or undetectable HIV viral load)." (PMID 23840511, 2013). "At baseline, 77% had HCV viral load greater than 800,000 IU/ml, 99% had CD4+ greater than 200 cells/mm3 and 10% had a diagnosis of cirrhosis." (PMID 23874441, 2013).
Cirrhosis (continued). "Interestingly, in this study, we observed that patients suffering from decompensated liver cirrhosis exhibited a decline in activation and exhaustion markers, HLA-DR and PD-1, on CD8+ and CD4+ T cells when compared to patients with compensated cirrhosis." (PMID 41028194, 2025). "Lending credence to this are findings from a study among people without HIV, where cirrhosis was also associated with a lower CD4+ cell count." (PMID 39656170, 2025). "Conversely, in patients with decompensated cirrhosis, CD4+ and CD8+ T cells exhibited heightened proliferative activity and showed a relative loss of activation and exhaustion marker expression compared with compensated cirrhosis." (PMID 41028194, 2025). "Moreover, immunocompromised hosts, including people living with HIV (PLWHIV) are at an increased risk of a chronic HEV infection trajectory, potentially accelerating the course to cirrhosis, especially in individuals with CD4 cell counts below 200 cells/μL." (PMID 39057763, 2024). "This includes a reduced potential of CD4+ lymphocytes and NK-cells in cirrhosis." (PMID 39444818, 2024). "Recent studies have shown that naive CD4+T cells can convert to TreGs in specific states (cirrhosis and cancer), which may be related to macrophages, further confirming the link between naive CD4+T cell interactions in macrophages and the Treg population." (PMID 39816386, 2024). "While no change in the distribution of αβT- and γδT-cells was observed between patients and controls, patients with cirrhosis showed a significant decrease in the CD4:CD8 T-cell ratio reflecting a higher number of CD8 + T-cells in the intestinal mucosa as compared to controls." (PMID 36881247, 2023). "Naïve CD4 + T cell induced by macrophage may differentiate into Treg in cirrhosis and they finally contributed to immunosuppressive TME." (PMID 36221095, 2022). "It has been hypothesized that HIV/HBV co-infected patient with low CD4 count is associated with a higher level of HBV replication and hastening progression to cirrhosis and HCC." (PMID 35875299, 2022). "Flow cytometry was used to determine the proportion and immunophenotype of CD4+HLA-G+ T cells from peripheral blood of 20 healthy controls (HCs) and 98 patients with cirrhosis (28 with stable cirrhosis (SC), 20 with chronic decompensated cirrhosis (CD) and 50 with AD)." (PMID 34344786, 2022). "Macrophage induced naïve CD4 + T cell to differentiate into Treg in cirrhosis and cancer." (PMID 36221095, 2022). "HCV infection has been suggested to negatively impact CD4+ cell count restoration and cirrhosis is associated with depressed CD4 cell counts, independent of HIV or HCV infection." (PMID 35222562, 2021). "RolyPoly showed that CD4 + T cell (β = 2.278 × 10–4, se = 1.149 × 10–4, P = 0.0259) was significantly associated with cirrhosis, whereas LDSC-cts identified no significant cell type." (PMID 33763117, 2021). "Although the adaptive CD4+ T cell response regulation by innate receptors, such as LSECtin, has been proposed in acute liver injury, the mechanisms leading to the specific increase in the Th17 subpopulation in cirrhosis remain to be elucidated." (PMID 32429209, 2020). "LSECs modulated their innate receptor’s transcriptional profile, bridged innate and adaptive immunity by inducing the expression of co-stimulatory molecules, cooperated in phagocytic tasks, and activated CD4+ T cells to differentiate effector Th responses in cirrhosis." (PMID 32429209, 2020). "In univariate analysis with fibrosis as a dichotomous variable (F0-F2 versus F3-F4), the following factors were associated with extensive fibrosis/cirrhosis: current or past excessive alcohol consumption, HCV time from diagnosis, nevirapine or lopinavir-based ART regimen and CD4 nadir." (PMID 27148964, 2016).
Cirrhosis (continued). "Forty-seven (36%) had major clinical contraindication to treatment (i.e. mental illness, cirrhosis, cardiac disease, low CD4+ cell count in HIV+ subjects), 18 (13%) refused the treatment, 7 (5%) moved to other Institute and 27 (20%) were not evaluated by infectious disease specialist." (PMID 24139133, 2013). "According to some reports, splenectomy in patients with cirrhosis might improve their impaired immune status by increasing interferon gamma production and reducing programmed cell death protein-1 (PD-1) expression in peripheral CD4+ T cells or CD8+ T cells." (PMID 38647617, 2024). "Hence, Whether TAGLN participate in cirrhosis via activating monocyte and CD4 T cell to achieve matrix remodeling and migration, as well as cell differentiation and invasion needs further investigation." (PMID 36725885, 2023). "Consequently, we hypothesized that naïve CD4 + T cell induced by Macrophage differentiated into Treg in cirrhosis and they finally contributed to immunosuppressive TME." (PMID 36221095, 2022). "Furthermore, we found that naïve CD4 + T cells convert into Treg in specific states (cirrhosis and cancer), which may be related to macrophage." (PMID 36221095, 2022). "Furthermore, HCV-related HCC had higher CD4+ TILs than HCV-related cirrhosis." (PMID 34566989, 2021). "The good immunovirological control may explain the marginal role of CD4 cell count and viral load with regard to comorbidities, and explain that the main prognostic criteria for this score were age, eGFR, cardiovascular disease, cirrhosis and low BMI." (PMID 29672628, 2018). "In addition to enhanced expression of mFasL on CD4+ T-cells in cirrhosis, sFasL serum levels were markedly elevated and we speculate that sFasL may participate in B-cell apoptosis in vivo in cirrhosis." (PMID 27857173, 2016). "Cirrhosis may suppress the immunity and may affect the CD4+ count." (PMID 21396133, 2011). "For instance, CXCR4 showed a strong positive correlation with activated CD4 T cells and effector memory CD8 T cells, highlighting the potential role of these cells in the immune landscape of cirrhosis." (PMID 41223189, 2025). "This review identified an increased proportion of senescent and exhausted CD4+ and CD8+ T cells in the liver of T2DM individuals with NASH or cirrhosis." (PMID 40362271, 2025). "Among people who died, the median age at death was 56 years (IQR, 53–57), 93% were male, the median CD4 count was 527 × 106/L (IQR, 363–868), 53% injected drugs during follow-up, and 30% had cirrhosis; 17% had current HCV infection at time of death." (PMID 39691290, 2024). "Immune cells obtained from ascites of four patients with cirrhosis were profiled using a panel of markers to enumerate T cells (CD3+, CD4+, CD8+), B cells (CD19+), monocytes/macrophages (CD14+), natural killer (NK) cells (CD16+CD56+), and neutrophils (CD15+)." (PMID 38474048, 2024). "Although this study focused on circulating lymphocytes in acute decompensation of cirrhosis, a single-cell RNA sequencing atlas of cirrhotic and uninjured livers revealed upregulation of CD52 gene in CD4+ T cells in cirrhotic livers." (PMID 39276679, 2024). "While PD1 expression in CD4+ and CD8+ T cells was upregulated in cirrhosis, the percentage of cells expressing CD69 was significantly reduced in CD4+ T cells." (PMID 39656486, 2024). "From the cirrhosis to cancer, IL16 and related ligand-receptor interaction (IL16-CD4) exhibited a significant difference in macrophage-naïve CD4 + T cell interaction." (PMID 36221095, 2022). "They observed normalization of cirrhosis induced alternation in levels of CD8+, CD4+, and CD25/CD4+ lymphocytes, and increased in number of CD3+, CD4+, and CD8+ TILs." (PMID 35892890, 2022). "The proportion of Treg cells (CD25+, CD127+ Low) in Th cells (CD3+, CD4+) was 11.74 ± 1.67% in HCC patients, 5.51 ± 1.22% in healthy group and 7.69 ± 1.07 in Cirrhosis." (PMID 33717135, 2021).
Cirrhosis (continued). "In patients with cirrhosis, CD8+ and CD4+ MAIT cells among the T cells were both lower compared with HCs." (PMID 34321090, 2021). "Pretreatment the mean age was 56.3 years, mean CD4 was 615, 72% had suppressed HIV RNA and 10% had cirrhosis by APRI or FIB‐4." (PMID 31339004, 2019). "The frequency of IL-21+CD4+ T cells in the CHB, HB-ACLF and cirrhosis groups was significantly higher compared with the HC group (P<0.05)." (PMID 24669269, 2014). "Despite increased phenotypical markers of T cell activation in cirrhosis, we observed a reduced fraction of T cells with cytokine responses to SEB as well as reduced TNF-α production in CD4+ and CD8+ T cells after stimulation with SEB." (PMID 23446058, 2013). "Despite a decrease in the lymphocyte population, the population of CD25-positive CD4+ and CD8+ T cells was expanded, and attenuated T cell responses to the SEB were more often observed in patients with cirrhosis and on-going inflammation." (PMID 23446058, 2013). "Despite CD4+ cell count not being statistically significant in multivariable analysis, the authors discuss the relationship between CD4+ cell counts and cirrhosis." (PMID 39656170, 2025). "Except for patients with HBV-ACLF, those with alcohol-induced ACLF and cirrhosis showed high expression of BTLA on CD4+ T cells (but not on CD8+ T cells), while patients with primary biliary cholangitis did not exhibit high expression of BTLA (n = 4)." (PMID 38418488, 2024). "For example, our previous research found that the level of PD-1+, TIGIT+, TIM-3 co-inhibitory molecules of adaptive immune CD4+, CD8+T, NK cells representing the exhaustion function gradually increased during the pathological process of chronic hepatitis B virus to cirrhosis and progressed HBV-HCC." (PMID 37201112, 2023). "More specifically, 34% of patients with decompensated cirrhosis were non-responders, while CD4-naïve, CD4 effector, B- and B-memory cells were lower in patients with decompensated cirrhosis." (PMID 36851329, 2023). "At baseline, NAFLD-HCC subjects had a higher percentage of regulatory T cells (Tregs; CD3+CD4+CD25+Foxp3+) compared to NAFLD-cirrhosis and non-NAFLD controls (P < 0.0001)." (PMID 33420074, 2021). "Levels of CD4+ and CD8+ effector/memory T cell activation may increase in the setting of HCV-mediated cirrhosis." (PMID 35062255, 2021). "In contrast, CD4+ T cells were increased and clustered at sites of fibrosis in the livers of the NAFLD patients (who were in the late stage of disease with evidence of NASH, cirrhosis and HCC) we studied." (PMID 33013934, 2020). "Thirty-one (31%) patients were immunocompromised: 12 with neoplasms (diagnosed during the last year), six with cirrhosis, six HIV-infected (two with CD4 T-cells under 200/mm3), three splenectomized patients, three with immunosuppressor drugs and 1 chronic renal insufficiency undergoing dialysis." (PMID 28526094, 2017). "We found that mCD40L expression was not significantly increased in peripheral CD4+ T-cells in cirrhosis but that plasma sCD40L levels were modestly elevated." (PMID 27857173, 2016). "Neither HIV status nor CD4 cell count, HIV RNA level or antiretroviral therapy use were associated with moderate or severe stiffness/cirrhosis." (PMID 26812065, 2016). "HCV genotype 1-positive treatment-naïve or pegIFN/RBV-experienced patients, with or without Child-Pugh A cirrhosis, CD4+ count ≥200 cells/mm3 or CD4 + % ≥14%, and plasma HIV-1 RNA suppressed on stable ART received open-label 3D + RBV for 12 or 24 weeks." (PMID 25394009, 2014). "Compared to healthy controls, patients with cirrhosis had higher circulating levels of LBP and IL-10, an expansion of peripheral blood CD14+ monocytes with low HLA-DR expression and an increased fraction of CD25-positive CD4+ and CD8+ T cells." (PMID 23446058, 2013).